TTTY13 (testis expressed transcript, Y-linked 13)
Synonyms: TTY13; NCRNA00136
Gene: Long non-coding RNA gene on chromosome Y (21,565,092 to 21,605,081, reverse strand). Ensembl gene ENSG00000184991.
Subcellular location: Membrane
Diseases named in the same sentence as TTTY13 in open-access papers:
TTTY13 is named in the same sentence as 1 disease in open-access papers, as found by Europe PMC text mining. Sharing a sentence is not in itself a finding about the gene and the disease.
TTTY13 shares sentences with these, for which no sentence is quoted: prostate tumor (1 paper).